HTRA1 (HtrA serine peptidase 1)
Diseases named in the same sentence as HTRA1 in open-access papers (continued):
Sharing a sentence is not in itself a finding about the gene and the disease.
cancer (53 papers, 2012 to 2026). A tumor composed of atypical neoplastic, often pleomorphic cells that invade other tissues. "This work aimed to examine the role of HtrA1 as a cell type-specific diagnostic biomarker or as an internal and external regulatory factor of diverse cancers." (PMID 34563186, 2021). "First of all, most of the studies are descriptive, preventing a causal inference between reduced HtrA1 levels and cancer." (PMID 29409460, 2018). "To date, four mammalian HtrAs (HtrA1-4) have been identified, and their dysregulation is associated with a number of diseases, including cancer, arthritis, neurodegenerative disorders, age-related macular degeneration, and pregnancy diseases." (PMID 28676687, 2017). "Downregulation of HTRA1 causes a multiple phenotypes that are hallmarks of cancer cells including increased proliferation of mouse embryonic fibroblasts (MEF), as well as chromosome and centrosome amplifications." (PMID 27388476, 2016). "Of particular interest was the identification of mutations in HTRA1 encoding a member of the trypsin family of serine proteases, involved in the degradation of extracellular matrix proteins, important in cancer progression and invasion." (PMID 27009842, 2016). "Human HTRA1 has been implicated in several severe pathologies including cancer, age-related macular degeneration, Alzheimer’s disease, arthritis and familial ischemic cerebral small-vessel disease." (PMID 27388476, 2016). "The tumour suppressor property of HTRA1 was correlated with its association to microtubule in cancer cells, which influences the cell motility." (PMID 25329061, 2014). "So far, the basis of HTRA1 downregulation in cancer is unclear, but loss of heterozygosity (LOH) or epigenetic modulations have been postulated as possible mechanisms." (PMID 23580433, 2013). "Notably, OMD+ fibroblasts exhibited high expression of HTRA1 (high-temperature requirement A1), a gene implicated in the transdifferentiation of normal fibroblasts into cancer-associated fibroblasts, further cementing their potential role in PDAC progression." (PMID 40092486, 2025). "The phenotypes of reduced HTRA1 expression such as acceleration of cell growth, centrosome amplification and polyploidy provide additional support for the model that proteolytic events are implicated in cancer biology." (PMID 27388476, 2016). "Thereby, the loss of HTRA1 may contribute to the aggressiveness and metastatic phenotype of cancer cells." (PMID 27809811, 2016). "Subsequently, PLA2R, PCDH7, HTRA1 and FAT1 antigens were found to be positive in patients with malignancy-associated MN." (PMID 38686366, 2024). "Muscle-secreted HTRA1 modulates cancer progression by attenuating TGF-β signaling required for angiogenesis." (PMID 38474424, 2024). "HTRA1, which has a role in various biological processes, including cancer, is intriguing for its involvement in musculoskeletal diseases." (PMID 38491514, 2024). "Due to the high expression of HDAC-1 and HDAC-6 in cancer cells, HtrA1 expression is low, as well as the expression of the retinoid X receptor (RXR)." (PMID 36263432, 2022). "The serine peptidase HtrA1 participates in cisplatin (CDDP) resistance by promoting a cancer stem cell phenotype in lung cancer." (PMID 36263432, 2022). "Previous studies have found that HTRA1 has a clear proteolytic capability and a recognised effect in cartilage degeneration, skeletal disorders and cancers, and HTRA1 can bind to TGF-β1 and degrade and regulate the amount of TGF-β1 in vivo and in vitro." (PMID 34946854, 2021). "Studies have explored the potential role of HtrA4 in cancer cell lines, reporting that HtrA4 promotes cell death by degrading XIAP and pro-caspase 7, which was shown previously for HtrA1 and 3 in cancer cells." (PMID 34639128, 2021). "Anti-cancer drugs, such as cisplatin and paclitaxel, are shown to upregulate HtrA1 which undergoes autocatalytic activation to initiate programmed cell death." (PMID 34639128, 2021).
cancer (continued). "Existing studies suggest that HtrA1 protects against diverse malignant tumors because of its antitumor activity." (PMID 34563186, 2021). "Recently, it has been reported that the down-regulation of HtrA1 promotes the survival, as well as the invasion and migration of cancer cells." (PMID 32878625, 2020). "Most importantly, the HtrA1/2 protein levels were decreased in tumors; specifically, a significant decrease occurred in the advanced cancer stage (III and IV)." (PMID 32486357, 2020). "The second aim of the meta-analysis was to assess overall survival in relation to low and medium-high HtrA1 expression in cancers." (PMID 29409460, 2018). "High temperature requirement factor A1 (HtrA1) plays an important role in cancer cell proliferation, migration, apoptosis, and differentiation." (PMID 30484491, 2018). "Accordingly, the purpose of this study is to evaluate the impact of HtrA1 downregulation in tumoral tissues on cancer progression and death in women with high-grade serous ovarian cancer." (PMID 30131069, 2018). "Functional investigation reveals that HtrA1 plays a critical role in cancer cell behaviors, including proliferation, migration, invasion, differentiation, and chemoresistance (10,12,22, )." (PMID 30484491, 2018). "Subsequently, several studies have demonstrated that the expression of HtrA1 is altered in various diseases including cancers." (PMID 30484491, 2018). "This study reports the results of a meta-analysis that was performed: to compare HtrA1 expression as mRNA and protein, in cancer tissue versus non-cancer tissue and to assess overall survival in relation to low or medium-high HtrA1 tissue expression." (PMID 29409460, 2018). "In particular, HtrA1 and HtrA3 have been suggested as tumor suppressors, because they are down-regulated in a number of cancers and this reduction is suggested to promote tumorigenesis." (PMID 28676687, 2017). "HTRA1 is a member of the serine protease family and a potential tumor suppressor that is downregulated in several cancer types." (PMID 26799320, 2016). "They documented significant differences in HtrA1 expression between normal and cancer tissue, whereas differences in FIGO stage, histological type or grade or menopausal state were not significant." (PMID 26035313, 2015). "HTRA1 has shown to be silenced through promoter hypermethylation, and proposed as a potential novel biomarker for diagnosis and prediction in several cancers." (PMID 24643221, 2014). "Epigenetic events have been postulated as other potential mechanisms to reduce HTRA1 expression levels in cancer." (PMID 23580433, 2013). "Expression of the serine protease HtrA1 is decreased or abrogated in a variety of human primary cancers, and higher levels of HtrA1 expression are directly related to better response to chemotherapeutics." (PMID 22761798, 2012). "Moreover, HTRA1 was reported to suppress angiogenesis in cancer stromal cells by activating the Notch pathway." (PMID 38334007, 2024). "A low HtrA1 expression in cancer tissues is related to the poorer survival of CRC patients." (PMID 34563186, 2021). "Here, we review the actions of HtrA1 in the pathogenesis of cancers, which may contribute to the development of therapeutic agents targeting HtrA1 in tumorigenesis." (PMID 34563186, 2021). "Since cancer patients who express low levels of HtrA1 have poorer responses to a few chemotherapy drugs, it is suggested that HtrA1 may serve as a potentially useful biomarker in selecting chemotherapy treatments." (PMID 34639128, 2021). "However, several genes were downregulated in CDDP resistant cells, including HtrA1, a cancer-related gene." (PMID 32878625, 2020). "In this context, the observed reduced level of HtrA1, a protein with a proapoptotic function, might be an element of cancer cell adaptation to avoid death during colorectal oncogenesis." (PMID 32486357, 2020). "A low level of HtrA1 or/and HtrA2 in cancer tissue correlated with poorer patient survival." (PMID 32486357, 2020).
cancer (continued). "Altogether, these data reveal that HtrA1 has an important effect in cancer that could potentially be targeted for therapy." (PMID 30131069, 2018). "The study found a significantly different HtrA1 expression in cancer and non-cancer tissue." (PMID 29409460, 2018). "It has been reported that overexpression of HtrA1 in several cancers could suppress cell growth, migration, and invasion, while HtrA1 knockdown in cancers induces resistance to conventional chemotherapeutics." (PMID 30484491, 2018). "HTRA1 is involved in several pathologies and some types of cancer." (PMID 27809811, 2016). "Mullany and co-workers investigated by an in vitro model whether HtrA1 downregulation influences cancer cell invasion." (PMID 26035313, 2015). "Finally, the investigation of liver and esophageal cancer also documented a longer OS in patients with a greater HtrA1 expression, whereas the difference found in endome-trial cancer was not significant." (PMID 26035313, 2015). "The 15 studies included in the review describe recent HtrA1 research in relation to cancer." (PMID 26035313, 2015). "Numerous studies revealed downregulation of the serine protease HTRA1 in cancer." (PMID 23580433, 2013). "Alternatively, new therapeutic strategies may exploit mechanisms to stimulate re-expression of HTRA1, although the basis of HTRA1 downregulation in cancer cells might be complex." (PMID 23580433, 2013). "However, during prolonged estrogenization and cancer development, significant reductions in HtrA1 RNA and protein were observed." (PMID 22761798, 2012). "However, the high similarity of the HtrA4 protein domain structure to that of HtrA1 and HtrA3, and implication of HtrA4 in oncogenesis suggest that it may function similarly to HtrA1/3 in promoting cancer cell death." (PMID 31546993, 2019). "A possible role for HtrA1 as a prognostic factor for cancer has also been hypothesized." (PMID 26035313, 2015). "Since HTRA1 loss was demonstrated to induce EMT and cancer cell invasion, these patients might benefit from demethylating agents or histone deacetylase inhibitors previously reported to lead to HTRA1 upregulation, or from novel small-molecule inhibitors targeting EMT-related processes." (PMID 23580433, 2013). "Thus, HTRA1 downregulation in cancer might in fact be explained by epigenetic mechanisms such as promoter methylation or histone-deacetylation." (PMID 23580433, 2013). "Finally, pathways important in cancer progression were affected by HtrA1 expression levels." (PMID 22761798, 2012). "Out of these, and based on the available literature data about their involvement in cancer and BCa, and positive correlation with stage, we have preselected NNMT, GALK1, and HTRA1 to be further tested in urine samples." (PMID 37834386, 2023). "Further study is required to unlock the complex interplay between HTRA1 and TGF‐β in a cell type–dependent manner, which is necessary for the understanding of HTRA1 as a multi‐functional regulator in cancers." (PMID 31867863, 2020). "Similarly to HtrA1 and HtrA2, HtrA3 exhibits proapoptotic function in certain pathological conditions; upon action of chemotherapeutic drugs, the mitochondria-localized HtrA3 is released into the cytosol and it participates in the stimulation of mitochondria-mediated apoptosis of cancer cells." (PMID 32486357, 2020). "The results shown that overexpression of HTRA1 promoted the proliferation, migration, and adhesion of PANC-1 and SW1990 cell, providing further evidence for suggesting that HTRA1 servers as a dual role in cancers." (PMID 38287020, 2024). "HTRA1 levels were also shown to be upregulated in the blood of PEMF-exposed and exercised mice, aligning with the efficacy of these sera to attenuate cancer growth, migration, and invasiveness." (PMID 38474424, 2024).
cancer (continued). "Although HTRA1 ranked the 26th in the list of differential expression genes, but after excluding those without prognostic significance, and those well-studied in cancers, HTRA1 is the one that best meet our requirement." (PMID 38740771, 2024). "Together, the double-inhibitory mechanism involving the molecular interaction of SERPINE2, HTRA1, and SDC4 as suggested here for NC cell migration in the Xenopus embryo might also regulate cancer cell migration in human metastasis." (PMID 38634469, 2024). "At the late stage, the HTRA1 level is low in cancer cells and unable to bind with TGF‐β and fails to inhibit TGF‐β signalling." (PMID 31867863, 2020). "Moreover, a decrease in HTRA1 and HTRA2 transcripts’ levels in cancers with a high level of microsatellite instability compared to microsatellite stable ones has been observed." (PMID 32486357, 2020). "GSN, HTRA1, and PDLIM5 were the prognostic genes in the grade 3 carcinoma." (PMID 32640634, 2020). "Xia and co-workers evaluated HtrA1 mRNA and protein in cancer and normal-appearing tissue using respectively IHC and ISH, two semi-quantitative techniques that were mainly applied to detect the cell type expressing HtrA1." (PMID 26035313, 2015). "A retrospective study of 333 nonmetastatic patients with locally advanced BC who underwent neoadjuvant chemotherapy (NACT) showed that high HTRA1 expression may indicate a lack of response to NACT and a predictor of increased risk of cancer recurrence and death." (PMID 34563186, 2021).
vasculopathy (6 papers, 2017 to 2024). "Interestingly, vasculopathy-associated mutations in HtrA1 that abolish its protease activity and ability to oligomerize, but harbor the anti-TGFβ-like KI domain, are unable to antagonize TGFβ signaling." (PMID 28992183, 2017). "In CAA type 1 and CADASIL, HTRA1 is recruited into the vascular Aβ and Notch3ECD deposits characterizing these vasculopathies." (PMID 35074002, 2022). "The reduced HTRA1 proteolytic activity due to pathogenic variants in the gene dysregulates the TGF-β signaling inhibition and leads to vasculopathy." (PMID 34946904, 2021). "However, there is a broader role of rare HTRA1 variants beyond CARASIL, which is caused by biallelic HTRA1 mutations: First, monoallelic mutations, which are linked to a milder vasculopathy with later onset, account for up to 5% of familial small vessel disease cases of unknown etiology." (PMID 39013852, 2024).
bacterial infections (5 papers, 2017 to 2026). "We additionally knocked down this host HtrA1 protein by siRNA approach, and observed that the HtrA1 interfering or not did not influence the E-cadherin expression, no matter with or without bacterial infection." (PMID 34482810, 2021).
colonic polyps (2 papers, 2016 to 2019). "Of 9 colonic polyps analysed, the Htra1 promoter was unmethylated in 4 polyps (polyps 13, 22, 145 and 147), methylated in 4 polyps (polyps 18, 98, 99 and 101) and partially methylated in one polyp (polyp 97)." (PMID 27388476, 2016).
musculoskeletal diseases (2 papers, 2021 to 2024). "For instance, HtrA1 is upregulated in various musculoskeletal diseases, coinciding with the increased fragmentation of several extracellular matrix (ECM) proteins that are known targets of HtrA1, which include fibronectin, type II collagen and decorin." (PMID 34639128, 2021).
autosomal recessive disease (1 paper, 2023). Autosomal recessive form of disease. "CARASIL is an autosomal recessive disease caused by homozygous mutations of HTRA1, and heterozygous mutations are often considered to be non-pathogenic." (PMID 37799144, 2023).
brain disease (1 paper, 2023). "Thus, further exploring the details of the regulation of HTRA1 activity will provide valuable insights into brain disease pathomechanisms and might lead to novel treatment strategies." (PMID 39081996, 2023).
HTRA1 also shares sentences with these, for which no sentence is quoted: cerebral autosomal dominant arteriopathy with subcortical infarcts and leukoencephalopathy (7 papers); schwannoma (7); pneumonia (6); gastric disease (5); mesothelioma (5); anthrax (4); campylobacteriosis (4); CARASIL syndrome (4); cerebral amyloid angiopathy (4); neurodegenerative disease (4); vascular dementia (4); age (3); frontotemporal dementia (3); Atrophy (2); bacteremia (2); Chlamydia infection (2); Chlamydial infection (2); cognitive deficits (2); enterocolitis (2); Fabry disease (2); gastric adenocarcinoma (2); infectious disease (2); inflammatory bowel disease (2); intrauterine growth restriction (2); lumbago (2); Lyme disease (2); migraine (2); neovascular age-related macular degeneration (2); prostate carcinoma (2); aggressive periodontitis (1).
A further 85 diseases each share a sentence with HTRA1 in 1 paper.